HOXA9 (homeobox A9)
Diseases named in the same sentence as HOXA9 in open-access papers (continued):
Sharing a sentence is not in itself a finding about the gene and the disease.
cancer (continued). "Hence, this study was conducted to explore the significant role of HOXA9 in multiple cancer types, with a particular focus on its involvement in immunological response, thereby offering new insights into anticancer therapy." (PMID 38904676, 2024). "Interestingly, the HOXA9 locus exhibited heterozygous amplification in more than 50% of patients across the 6 TCGA cancer types, with READ (64.24%) and ESCA (65.21%) showing the highest percentages." (PMID 38904676, 2024). "However, further studies are needed to determine the effectiveness of other antineoplastic drugs that target HOXA9 in cancer treatment." (PMID 38904676, 2024). "Targeting HOXA9 has emerged as a promising strategy with the potential to impede cancer progression, offering new perspectives for future research and clinical interventions in diverse cancer types." (PMID 38904676, 2024). "HOXA9 was significantly upregulated in 9 tumors and downregulated in 2 cancers." (PMID 38904676, 2024). "Furthermore, we have also discussed the existing therapeutic options and accompanying challenges in HOXA9-targeted therapies in different cancer types." (PMID 38062297, 2023). "Our findings revealed that miR-633/HOXA9 mediated the function of PCED1B-AS1 in this cancer." (PMID 35176937, 2022). "These post-transcriptional events show alternative aspects of HOXA9 regulation and might offer novel therapeutic opportunities in cancer treatment." (PMID 36376832, 2022). "In addition to providing insights into the regulatory control of cancer cell fate through HOXA9, our computational network model recapitulates the disease symptoms using well-known hematopoietic transcription factors." (PMID 36192425, 2022). "HOXA9 is a kind of homeoproteins which abnormally expressed aberrantly in human cancers." (PMID 34416888, 2021). "WNT6 and HOXA9 co‐expression in all cancer types with available RNAseq data in TCGA." (PMID 31923345, 2020). "Therefore, the effect of HMGA2 in TET1 expression and the subsequent effect of TET1 in HOXA9 expression is known as the HMGA2/TET1/HOXA9 signalling pathway, which has a role in the invasion and metastasis of cancer cells." (PMID 33375038, 2020). "Many studies have established the function of HOXA9 in cancer cells." (PMID 31043660, 2019). "Finally, HOXA9 was also able to stimulate cancer cells to attach to peritoneal mesothelial cells via p-cadherin encoded by the CDH3 gene." (PMID 31382546, 2019). "Interestingly, our expression array data showed an HOXA9-mediated enrichment of genes involved in several important hallmarks of cancer." (PMID 25762636, 2015). "Furthermore, MIXL1 expression is detected in the cancer genome atlas (TCGA) AML samples in a pattern mutually exclusive from that of HOXA9, CDX2 and HLX suggesting the existence of a core, yet distinct HOX transcriptional program." (PMID 25544748, 2014). "Notably, HOXA9 was aberrantly expressed in 11 out of 33 GDC-TCGA cancer types." (PMID 38904676, 2024). "Hence, it is worth studying the miRNA-mediated regulation of HOXA9 in different cancer types." (PMID 38904676, 2024). "Quantitative RT–PCR (qRT-PCR) further showed that Bcat1 (related to BCAA metabolism) or Hoxa9, Ccnt1, Pbx1, Rora and Pbx3 (related to transcriptional misregulation in cancer) were significantly reduced in P2x1-null LICs, suggesting that these genes may act as downstream targets of P2X1." (PMID 36418376, 2023). "Moreover, as a known transcription factor in development and cancer fields, the roles of HOXA9 in cutaneous carcinogenesis remained unknown." (PMID 29662084, 2018). "Given our data implicating HOXA9 as a key molecule in mediating several aspects of cancer aggressiveness and stem cell characteristics, we hypothesized that HOXA9 may also play an important role in the tumorigenic process, possibly facilitating carcinogenesis initiation." (PMID 25762636, 2015).
cancer (continued). "Analysis of the HOXA9 gene revealed a positive correlation with PBX1, PBX2, PBX3, and MEIS1 in all cancer types except for STAD among the 11 studied genes, suggesting enhanced binding of HOXA9 to the promoter region of target genes." (PMID 38904676, 2024). "MiR-126 alters the biological functions of some genes such as PI3K, EGFL7, HOXA9, sKRAS, CRK, ADAM9, IRS-1, SOX-2, SLC7A5, and VEGF, as well as involves in inflammation, cell migration, angiogenesis, recurrence of cancer, and metastasis." (PMID 38445462, 2024). "Specifically, statistically significant MPMR elevations, with fold changes of 2.01, 1.36, and 2.61, were identified on the promoters of HOXA9, the HOXD3 genes of cancer patients, and the RASSF1A promoter of non-cancer patients, respectively." (PMID 39123492, 2024). "Collectively, these findings indicate that the MSI2/HOXA9 fusion protein has oncogenic activity and can cooperate with BCR-ABL to drive cancer progression." (PMID 38234720, 2023). "In LSK-derived MLL-cancer stem cells, the PRMT1 function is coregulated by β-catenin and Hoxa9; by mediating similar signaling pathways as β-catenin and Hoxa9, PRMT1 is directly involved in leukemic cell self-renewal." (PMID 36358861, 2022). "We discovered that HOXA4, HOXA9, and HOXD10 have a role in regulating colonic SC renewal and are aberrantly expressed in cancer SCs (CSCs)." (PMID 35743243, 2022). "The performance of all the two-gene marker panels (HOXA9 + SOX1) and (HIC1 + SOX1) was found significant and the gene panels differentiated cancer vs normal with a higher accuracy in serum samples." (PMID 34778370, 2021). "These lines were selected based on their differential expression of HOXA9, MEIS1, and PLA2G4A in the Cancer Cell Line Repository sequencing data." (PMID 34502319, 2021). "Methylated HOXA9, SOX1, and HIC1 exhibited the highest sensitivity, specificity, AUC, and accuracy for cancer detection in both singleplex and multiplex MethyLight assay, thereby asserting that their promoter hypermethylation was highly cancer-specific." (PMID 34778370, 2021). "Among these transcription factors, HOXA9 and PBX1 have been reported to function as drivers in drug resistance of multiple cancer types." (PMID 32703314, 2020). "In conclusion, HOXA9, a positive regulator of RUNX2, can enhance calcification and cancer migration and invasion ability in PTC, dependent and independent of RUNX2." (PMID 31043660, 2019). "It has been reported that HOXA9 and HOXC8 are involved in glycolysis and play important role in cancer metabolism." (PMID 31013831, 2019). "The fact that Hox genes such as HOXD10, HOXA9, HOXD9, HOXD13 are strongly upregulated in Huh6 cells on the CAM reflect a profound reprogramming of cancer cells in a permissive, growth promoting in vivo microenvironment." (PMID 29662633, 2018). "The analysis for KEGG pathway indicated the involvement of HOXA9 and HOXA10 in the “Transcriptional misregulation in cancer”, playing a possible role in cell differentiation resistance." (PMID 29101335, 2017). "Expression of miR-126 is decreased in various cancer cells, and it has previously been regarded as a cell growth suppressor that acts on IRS-1, HOXA9 and p85β." (PMID 21464990, 2011). "Our data support the view that promoter hypermethylation is a common mechanism involved in ovarian carcinogenesis and four target genes, HOXA9, HOXB5, SCGB3A1, and CRABP1, novel to this cancer type are identified." (PMID 17623056, 2007). "The methylation frequencies of HOXA9 and SCGB3A1 were higher among relatively early-stage carcinomas (FIGO I-II) than among carcinomas of later stages (FIGO III-IV; P = 0.002, P = 0.020, respectively)." (PMID 17623056, 2007).
cancer (continued). "Additionally, experimental research is needed to elucidate the detailed mechanisms by which HOXA9 and SOX1 methylation influence cancer progression, and to explore its potential as a therapeutic target." (PMID 40699796, 2025). "The specific mechanism through which HOXA9 contributes to oncogenicity in distinct cancer types is still not understood." (PMID 38904676, 2024). "The important role of HOXA9 in AML and solid tumors make it a potential target in cancer therapy." (PMID 36376832, 2022). "The three best-performing genes exhibited individual frequencies of 53.0–71.0% in serum CFDNA, and the multiplex assay for these genes were identified to discriminate serum from cancer patients and healthy individuals (area under the curve: HOXA9+HIC1 = 0.95, HIC1+SOX1 = 0.93 and HOXA9+SOX1 = 0.85)." (PMID 34778370, 2021). "When MEIS inhibitors are used in cancer studies, downregulation of Hoxa9 could be beneficial because MEIS1 is known to cooperate with HOXA9 in carcinogenesis." (PMID 32409701, 2020). "In conclusion, HOX genes are frequently engaged in NUP98 fusion, thus mediating cancer progression, by acting as fusion partner genes of NUP98, such as HOXA9 and HOXD13, or by mediating the effect of other NUP98 fusions as their target genes in a wide range of hematologic malignancies." (PMID 31013831, 2019). "Despite this, HOXA9 was for a long time not targeted to treat cancer, mainly since, as a transcription factor, it belongs to a class of protein long considered to be an “undruggable” target; however, things have now evolved." (PMID 31213012, 2019). "In summary, this work reveals HOXA9 as a novel direct regulator of HOTAIR, and establishes HOTAIR as an independent prognostic marker, providing new therapeutic opportunities to treat this highly aggressive cancer." (PMID 29644006, 2018). "Besides, we demonstrated that HOXA9 is essential for the expression of the zinc finger protein ZEB1, a master regulator of cancer metastasis." (PMID 28969042, 2017). "In addition, of all the 31 Onco/TSGs harboured sHyperMethyl and sHypoMethyl in their gene body, 7 genes (HOXD11, TAL1, HOXA9, PAX5, FOXP1, FOXO1, TERT) were reported to serve as potential DNA methylation-based biomarkers for non-invasive early cancer diagnosis." (PMID 37393582, 2023). "Furthermore, functionally, ectopic expression of TET1 catalytic domain in cancer cell lines reactivated silenced tumor-suppressor genes (DLit2, ZNF382, HOXA9, and DKK1) and significantly suppressed clonogenicity of cancer cells compared to the catalytically dead mutant." (PMID 34209564, 2021). "Therefore, HOXA9 might be an indicator of poor prognosis in PDAC and other cancer types." (PMID 39462379, 2024). "Therefore, no universal model exists to predict the exact role of HOXA9 in a cancer type." (PMID 29662084, 2018). "Serum promoter methylation of homeobox A9 (HOXA9) and hypermethylation in cancer 1 (HIC1) showed a combined AUC of 0.95, and no hypermethylation was observed in sera from matched cancer-free control women." (PMID 38275400, 2024). "EPHB4 on the other hand has been shown to be transcriptionally regulated by HoxA9 in endothelial cells, but no information is available about the transcription factors involved in regulating expression of EPHB4 in cancer cells." (PMID 25886373, 2015).
hematologic malignancies (6 papers, 2018 to 2025). "PIM1, a serine/threonine kinase, is known to be overexpressed predominantly in hematologic malignancies and is a downstream target of HOXA9, especially in AML with FLT3-ITD mutations." (PMID 40746924, 2025). "We further propose the prognosis marker role of the HOXA9 gene to another blood disorder, MPN." (PMID 36192425, 2022). "Thus, HOXA9 may act as an oncogene in hematologic malignancies." (PMID 29662084, 2018). "It is no surprising that HOXA9 always acts as an oncogene in hematologic malignancies and positively regulate pro-carcinogenic HIF-1 expression." (PMID 29662084, 2018).
adenocarcinoma (4 papers, 2019 to 2024). A common cancer characterized by the presence of malignant glandular cells. "Combined with HOXA9, the detection rates of LungMe® in adenocarcinoma were further improved from 79.7% to 87.0%." (PMID 36176402, 2022). "SOX17, TAC1, CDO1, HOXA9 and ZFP42 were the 5 genes that were identified in the Cancer Genome Atlas (TCGA) with highly prevalent DNA methylation in lung squamous and adenocarcinoma, but not in normal lung tissue." (PMID 38315228, 2024).
infection (4 papers, 2013 to 2022). The state of being infected such as from the introduction of a foreign agent such as serum, vaccine, antigenic substance or organism. "Bone marrow stem cells from these animals were immortalized by infection with virus encoding constitutively expressed HoxA9 or Nup98-HoxA9, in the continuous presence of IL-3 and GM-CSF." (PMID 24177192, 2013). "HoxB8 and HoxA9 infection induced rapid proliferation of wild type cells but only HoxB8 induced proliferation of Bcl-2−/− cells and permitted the establishment of cell lines." (PMID 24177192, 2013). "After transduction with HoxA9 lentivirus and selection for infection, equal cell numbers of Bcl-2+/+, Bcl-2+/− and Bcl-2−/− cells were seeded in liquid culture containing cytokines and cell numbers were assessed over 9 days." (PMID 24177192, 2013).
blood cancer (2 papers, 2018 to 2022). "We hypothesise in this work that, as a consequence of the underlying gene network, the expression of HOXA9 could be used to stratify patients according to risk with blood cancers affecting the myeloid lineage." (PMID 36192425, 2022).
HOXA9 also shares sentences with these, for which no sentence is quoted: cyst (5 papers); gastric cancer (5); myelodysplastic syndrome (4); uveal melanoma (3); Ewing sarcoma (2); head and neck cancer (2); Infertility (2); keloid (2); multiple myeloma (2); neuroblastoma (2); Papillary Thyroid Carcinoma (2); Pleural effusion (2); rectal adenocarcinoma (2); renal carcinoma (2); acute megakaryoblastic leukemia (1); angiosarcoma (1); astrocytoma (1); autism (1); B-cell acute lymphoblastic leukemia (1); basal cell carcinoma (1); brain glioma (1); CNS tumors (1); cutaneous melanoma (1); fibrosarcoma (1); germinoma (1); hemangioblastoma (1); hematologic cancers (1); Hematuria (1); hypertrophy (1); idiopathic pulmonary fibrosis (1).
A further 24 diseases each share a sentence with HOXA9 in 1 paper.